IL10 (interleukin 10)
Diseases named in the same sentence as IL10 in open-access papers (continued):
Sharing a sentence is not in itself a finding about the gene and the disease.
viral infection (continued). "As TIGIT ligation is functionally linked to IL-10 expression that is known to both promote virus persistence in vivo, but also limit adverse immunopathological damage, the TIGIT pathway might represent an important regulatory gatekeeper for the control of viral infections." (PMID 32152316, 2020). "In the late phase of acute virus infection, type II IFN and several other cytokines including TNF-α and IL-10 are released by immune cells such as CD8+ T cell cells." (PMID 31263684, 2019). "We also observed an increment in IL-10, the Th2 cytokine; however, the IL-10 levels were significantly lower compared to IL-17 and IFN-γ, indicating elicitation of Th1 type of immunity, which is important for the clearance of viral infections." (PMID 29391053, 2018). "Paradoxically, during some acute viral infections highly activated, pro-inflammatory CD8+ T cells can also produce IL-10 and even represent a major source of IL-10 in infected organs." (PMID 26991092, 2016). "Together, these data suggest that locally produced IL-10 enhances the recruitment of CCR2+ monocytes, which localize to areas of viral infection and reduce viral titers in the skin." (PMID 26991092, 2016). "We next measured levels of immunomodulatory mediators in lung homogenates and report that viral infection in fibrotic lungs (Bleo+MHV-68) led to a significant increase in lung levels of CCL2, IL-1β, TNFα and IL-10 above the levels detected for Bleo lungs." (PMID 26138704, 2015). "Viral IL-10 can reduce the ability of DCs to present antigen via inhibition of anti-apoptotic factors but also potentially drives DCs toward a phenotype that could induce T cell anergy and therefore render the adaptive immune response less responsive to the virus infection." (PMID 25071749, 2014). "After pdmH1N1 virus infection, cigarette smoke exposed mice had significantly higher production of IL-1α, IL-1β, IL-2, IFN-γ, KC, RANTES on day 3; IL-5, IL-10 and MIP-1α both on day 1 and day 3 in the lungs than the control mice." (PMID 24465940, 2014). "Extrinsic ADE infection contributes to a high rate of viral infection in Fcγ receptor-bearing cells, whereas the intrinsic ADE effect via IL-10 suppresses the activation of the IFN-mediated antiviral response." (PMID 23800014, 2013). "Our data indicate that the induction of IL-6, IL-8, IL-10, CCL-5, as well as IFN-β, were apparent at the earliest stages of viral infection even before ERK1/2 was further activated." (PMID 22279582, 2012). "We also investigated the expression of IL-10, for its role in modulating B cell function and humoral responses, type I IFN-β, which plays a pivotal role in the host immune response against viral infections, and MxA, an important mediator of type I IFNs." (PMID 21961056, 2011). "For instance, with a low dose of pneumococcus, the preceding virus infection appeared to be determinative in skewing the MoDC cytokine production towards suppression of TNF-α, IL-6 and IL-10 as stimulated by the bacteria." (PMID 21771345, 2011). "Nonetheless, increased levels of IL-10, IFN-γ and TNF-α indicate the presence of fungal, bacterial or viral infection." (PMID 21619669, 2011). "We found that IL-10 signaling facilitates WNV infection and suppresses antiviral cytokine production in response to viral infection." (PMID 19816558, 2009). "IL-10 is an important immunomodulatory cytokine, and recent experiments in the LCMV model of chronic viral infection showed that manipulating levels of IL-10 alone was sufficient to dictate LCMV clearance or persistence." (PMID 18554409, 2008). "Using viral infection methods, we genetically modified macrophages to overexpress the anti‐inflammatory cytokine IL‐10, thereby enabling its extracellular secretion without compromising their physiological functions." (PMID 39801756, 2025).
viral infection (continued). "IL-10 could suppress the production of pro-inflammatory cytokines (e.g., TNF-α, IL-6), thereby limiting inflammation and tissue damage during acute viral infection (e.g., SARS-CoV-2, H1N1, respiratory syncytial virus (RSV))." (PMID 41156600, 2025). "During viral infection, PCV2 directly infects porcine alveolar macrophages, which may lead to IL-10 production through the MyD88-NF-κB pathway." (PMID 41156600, 2025). "The resulting network revealed a highly interconnected core centered around key cytokines—including IL-6, IL-1β, IL-10, TNF-α, IL-18, and GM-CSF—which function as pivotal hubs driving the host inflammatory response and immunopathogenesis in both viral infections." (PMID 41366310, 2025). "Elevated IL-8 and IL-10 are linked to SCZ and BD, though not all viral infections with these cytokine increases lead to corresponding mental disorders." (PMID 39206043, 2024). "IL-10 inhibits the production of key cytokines such as IL-2 and interferon-γ (IFN-γ) by T helper type 1 (Th1) cells, which are essential for the control of viral infections." (PMID 39459871, 2024). "The outcome of virus infection could be affected by the induction of innate immune cytokines, including IFNs, TNF-α, IL-10, and TGF-β1." (PMID 38962699, 2024). "It seems that the immune response was normal outside the viral infections, and no minimal variation in IL-10 and IL-31 was noticed in the end of the study." (PMID 38397331, 2024). "The simulation result also predicted that the constructed vaccine could generate numerous forms of cytokines, including IFN-γ, IL-23, IL-10, and IFN-β; some of the most critical cytokines for producing an immune response to viral infections." (PMID 37322049, 2023). "Concomitant blockade of IL-10 and PD-1 immune checkpoint in a mouse model of lymphocytic choriomeningitis virus (LCMV) increases the efficacy in restoring antiviral T cell responses and controlling persistent viral infection." (PMID 37359549, 2023). "NK cells can secrete IL-10 during viral infections and indirectly affect T cells by non-contact-dependent mechanisms, inhibiting antigen-specific T cell proliferation." (PMID 38022497, 2023). "To explore the effect of SPJ treatment on cytokine expression, we used real‐time PCR and observed that viral infection led to increased expression of cytokines and chemokines, including IL‐6, IL‐1β, TNF‐α, IL‐10, IFN‐α, IFN‐β, and IFN‐γ, as well as CXCL‐2, CXCL‐10, CCL‐2, CCL‐3, and CCL‐5." (PMID 37544014, 2023). "Conversely, persistent viral infection results in the upregulation of IL-10, leading to impairment of the T cell response and a lack of efficient clearance of pathogens from the host." (PMID 36362383, 2022). "We also observed that the production of IL-10 was rarely seen from cells that were also producing IFNγ in response to HCMV stimulation, which is unusual as dual IL-10 and IFNγ-producing CD8+ T cells are often described in other virus infections." (PMID 36558866, 2022). "We focused on the IL-10–mediated regulation of the immune response by various B cell subsets (including Bregs), production of other cytokines by B cells, antigen presentation, and TLR-mediated activation of B cells during viral infections." (PMID 34293057, 2021). "Overall, in viral infections, the absence of IL-10 results in demyelination and cell death, while the presence of IL-10 protects against tissue damage." (PMID 34484241, 2021). "Murine CMV may have repressed the ability of GWAT to produce and release IL-10, highlighting the importance of future studies to investigate the interaction between WAT depots and other tissues during viral infections with MCMV and other viruses." (PMID 32455939, 2020). "The virulent ASFV SY18 induced continuous increase of almost all key pro-inflammatory cytokines involved in virus infection but not the anti-inflammatory cytokines, IL-10 and TGF-β1, which, at the first time, clearly drew an image of a cytokine storm." (PMID 33553280, 2020).
viral infection (continued). "Interestingly, it has been reported that IL-10 decreases both CM and EM development specifically within the CD4+ T cell compartment in response to viral infection." (PMID 31907034, 2020). "The reduced iCa2+ influx in chronic Hep B/ Hep C derived CD8+ T cells suggested a significant change in early TCR down-stream events, specifically iCa2+ influx, following persistent viral infection that effects pro/suppressive cytokine secretion such as IFN-γ and IL-10." (PMID 32210950, 2020). "For example, macrophage-driven expression of antiinflammatory IL-10 in a mouse model can attenuate the long-term effects of prenatal viral infection, but in the absence of inflammatory stimulus, IL-10 itself precipitates offspring behavioral abnormalities." (PMID 32174851, 2020). "Tc1 cells known to be important for clearance of viral infections through secretion of IFN-γ and cytolytic molecules Gr B and Perforin-c have been shown to change phenotype and secrete IL-10 and this compromised cytotoxic status has been shown to precipitate chronic viral infection(s)." (PMID 32210950, 2020). "Upon viral infection such as with MCMV, depletion of IL-10 leads to enhanced ALT activity." (PMID 31143178, 2019). "The anti-inflammatory cytokine IL-10 was elevated in PCLS from both groups upon viral infection with 218 vs. 348 pg/mg in the non-sensitized group, and 1112 vs. 1530 pg/mg in the HDM-sensitized group." (PMID 31640701, 2019). "Similar to what we observed for AB14 (H5N1), the IL-18 gene transcript was not upregulated in response to viral infection, whereas the gene transcription of the anti-inflammatory cytokine IL-10 dramatically increased from 2 to 7 d.p.i." (PMID 30813415, 2019). "There is a possibility that IL-4, IL-8, IL-10, IL-12, and TNF-a might serve as biomarkers for infections and that IL-2, IL-8, or IL-10 is potentially able to distinguish between bacterial and viral infections." (PMID 29531507, 2018). "Up-regulation of Th1 cytokines (e.g. IL-12, INF-γ) and down-regulation of Th2 cytokines (e.g. IL-4, IL-10) and nitric oxide (NO) were the major targets to retain the th1/th2 balance corrupted by HCV viral infection and have an adequate anti-HCV cellular immune response." (PMID 27577059, 2016). "The current study shows that exposure to AvCystatin leads to enhanced recruitment of IL-10-producing CD4+ T cells in viral infection; however, FoxP3 expression did not coincide with IL-10 production in the regional lymph nodes." (PMID 27560829, 2016). "The interactions between innate IFNs, pro-inflammatory cytokines, and IL-10 during acute viral infections are not well defined, and current data are contradictory." (PMID 25430775, 2015). "Elevated IL-10-producing B cell frequency is not a feature of all chronic virus infections, as we did not observe this in chronic untreated HCV mono-infection." (PMID 24586620, 2014). "However, our group as well as others have shown that during human viral infections, CD19+CD24hiCD38hi B cells are highly IL-10 competent and exert a regulatory function." (PMID 24739950, 2014). "On an other hand, it may also be due to higher production of immunosuppressive IL-10, which has been found to correlate positively with DHS and negatively with serum IgG3 titres in male patients with other viral infections." (PMID 23302155, 2013). "The cytokine environmental balance (i.e., decline in the INFγ : IL-10 ratio) in challenge condition (i.e., influenza or other viral infections) could decline the CD8+ cytotoxic ability, thus conducing to high IL-10 response to virus challenge." (PMID 24260712, 2013). "IL-10 can induce IFN-γ secretion by NK cells and increased IL-10 may provide positive feedback to increase IFN-γ secretion during viral infection." (PMID 22435642, 2012). "Importantly, during chronic virus infection in vivo, as demonstrated in the LCMV model, IL-10 antagonizes antiviral immunity and promotes virus persistence." (PMID 23012619, 2012).
viral infection (continued). "Despite the mounting evidence in other systems, a role for host-produced IL-10 during chronic viral infections has not been carefully studied until recently." (PMID 17570849, 2007). "Also, IL-10 was highly expressed, which has been involved in counteracting the pro-inflammatory effects of TNF-α and IL-6 while mitigating glutamate toxicity, factors responsible of neuropathogenic processes, including viral infections." (PMID 41474758, 2025). "The potential inflammatory mechanisms may be as follows: Tph cells are multifunctional, capable of secreting a variety of cytokines, including interleukin 21 (IL-21), IL-10, interferon g (IFN-g), thereby playing a role in controlling bacterial and viral infections within the body." (PMID 40144882, 2025). "Notably, IL-10 was increased in inflammatory diseases, and IFN-γ was increased in viral infections." (PMID 40281902, 2025). "The levels of IL-1β and IL-33, cytokines with important roles in metabolic homeostasis, viral infection, inflammation and carcinogenesis, are not statistically significant different in the two groups, as well as the levels of the immunoregulatory IL-10 and immunostimulatory IFN-γ." (PMID 38961336, 2024). "Thus, subchronic exposure to PFOA resulted in suppressed IL-10 levels, regardless of viral infection." (PMID 37600798, 2023). "Even though CLEC2.Fc was unable to inhibit virus infection and replication, CLEC2.Fc inhibited the expression of IL‐6, CXCL2, CXCL5, CCL2, and IP‐10 at day 3 and day 5 post‐infection, and the expression of TNF‐α, IFN‐γ, IL‐10, and CXCL1 was also suppressed at day 5 post‐infection (red columns)." (PMID 37211986, 2023). "Finally, we found a positive regulation of genes related to immune response to virus infections (Type I Interferons, inflammatory cytokines (IL-6, TNF and NF-κB), NLRP3 inflammasome, anti-inflammatory cytokines (IL-10), and cell death pathways (pyroptosis and apoptosis)) in RA individuals." (PMID 37628893, 2023). "In fact, based on the findings of Blackburn and Brooks, we speculate that the actual cause of persistent virus infection is TGF-β and not IL-10." (PMID 36914565, 2023). "Sustained IL-10 and MCP1 high levels found in cardiac and pancreatic tissues have been shown to exert an immunosuppressive activity and promote a T helper/Th2 inflammatory response switch resulting in an altered immune modulatory response and potentially promoting a persistent viral infection." (PMID 36016091, 2022). "Unlike the other viruses, IL-10 in HAdV infection serves as the best predictor for disease progression with the highest area under the curve (AUC) of 0.944, indicating that predictors for different viral infections were virus specific." (PMID 34163488, 2021). "On the other hand, the significant increase in the ratios of total CD3+ and CD4+ T cells and the ratios of activated (CD25+) CD8+ T cells and the level of the Th1 cytokine and inhibitor IL-10 between the negative control and positive control mice that had an only viral infection." (PMID 34349145, 2021). "Therefore, further studies will be needed to define the phenotype of B cell subsets involved in IL-10 production during viral infections as currently no specific marker is available for the many B cell subsets that can produce IL-10." (PMID 34293057, 2021). "We speculate that the increased expression of IL-10 observed in the HIV-positive population could play a role in the course of SARS-CoV-2 infection, as IL-10 has emerged as a key regulator of immune responses against viral infections." (PMID 34831410, 2021). "IL-10 was elevated in severe but not mild cases after the virus infection; IL-10 at week 1 may predict patient outcomes." (PMID 34646263, 2021). "Moreover, virus infection enhanced the expressions of TNF-α, IL-1β, IL-6, IL-10, IFN-α, and IFN-β." (PMID 33827620, 2021).
viral infection (continued). "Indeed, while inflammatory cytokine production was negligible (IL-1β, TNFα) or not significantly increased (IL-6), the production of IL-10 and of TNFRs was significantly enhanced upon viral infection." (PMID 34901152, 2021). "Therefore, the timing and balance of IL-10 and Type I IFN expression could be important to control viral infection." (PMID 32849638, 2020). "Thus, it is implicit from these results that simple reduction of IFN-γ and increased production of IL-10 during viral infection(s) alone do not lead to suppressed immune system or to disease chronicity." (PMID 32210950, 2020). "In Hep B however since viral replication is high, IL-10 secreting cells do not allow viral clearance subsequently leading to liver pathology while a robust Tc1 response would allow viral clearance as is mandated for any viral infection clearance." (PMID 32210950, 2020). "Thus, IL-10 is pleiotropic and has immunosuppressive functions independent of the PD-1/PD-L1 axis during persisting virus infections." (PMID 31263684, 2019). "Activation of IFN is the earliest transcriptional response to viral infection; the IFN-λ–IL-10–CBFβ axis might act as a quick response in fighting against HBV in the early stage, and when HBV is uncontrolled in the later stages (e.g., in HBV patients), IFN-λ signaling is inhibited." (PMID 29523836, 2019). "In addition, although the absence of IL-27 consistently reduces IL-10 producing CD4 T cells in multiple types of viral infections, the outcome for viral control is highly variable." (PMID 30044874, 2018). "Finally, other immunoregulatory cytokines like IL-10 and IL-33 that play important roles in the control of viral infections are highly expressed by MΦs but not by other myeloid subsets, particularly after WNV infection." (PMID 29408905, 2018). "Therefore, it is tempting to speculate that pretreatment of IFN-I and FL during pDC expansion induces the production of TGFβ or IL-10 which, in turn, attenuates IFN-I production from pDCs in response to CpG or viral infections." (PMID 26263178, 2015). "Our findings demonstrate that activation of Fas modulates poly I:C-induced cytokine production in both a positive (IP-10) and a negative (TNFα, IL-8, IFN-β, IL-10) manner implicating a role for Fas ligation in tailoring the immune response following viral infection." (PMID 25849666, 2015). "Understanding the dynamics of IL-10 induction and the role infection of DCs may play in promoting chronic LCMV infection has been a highly active area of research as it may have significant implications in a variety of clinically relevant viral infections." (PMID 24613988, 2014). "We observed robust induction of IL-10 in cDCs but not in pDCs, suggesting that the major DC subtype that produces IL-10 in our experimental system is cDCs, This result is consistent with the previous reports that pDCs do not produce IL-10 upon virus infection or TLR stimulation." (PMID 23667643, 2013). "Based on our data, we propose that IL-10 produced upon FMDV infection suppresses CD4+ T cell activity, as we have previously shown during acute infection, promoting the activation of virus-specific B cells to produce neutralizing antibodies, clearing the viral infection." (PMID 19478852, 2009). "The previous studies hold that type I IFNs increased the anti-inflammatory IL-10 and decreased pro-inflammatory cytokines in the virus infection, which could also explain that the type I IFNs was not effective against the virus replication with the PEDV infection." (PMID 37924089, 2023). "Vice versa we could verify that TIGIT blockade leads to the diminished expression of IL-10 by CD8+ T cells during chronic infection, which indicates that TIGIT is involved in shifting the cytokine balance toward a more IL-10 dominated immune response in the context of viral infections." (PMID 32152316, 2020).